BRCA1 (BRCA1 DNA repair associated)
Diseases named in the same sentence as BRCA1 in open-access papers (continued):
Sharing a sentence is not in itself a finding about the gene and the disease.
ovarian carcinoma (continued). "Of note, retrospective analysis of results from a clinical trial demonstrated that olaparib also improve progression-free survival (PFS) in the patients with BRCA1/2-wild type ovarian cancer." (PMID 36284291, 2022). "Dobutamine treatment only induced mild cAMP production, indicating that ovarian cancer cells with normal BRCA1 maintain relatively low levels of ADRB1." (PMID 35517499, 2022). "The c.5266dupC, c.5177_5180delGAAA, and c.5251C > T variants in BRCA1 and the c.2808_2811delACAA and c.1138delA variants in BRCA2 were the most common variants among breast and ovarian cancer patients from Brazil." (PMID 35918668, 2022). "The use of Poly ADP-Ribose Polymerase (PARP) inhibitors is being expanded as therapeutic alternative in multiple types of cancer beyond BRCA1/2 mutant breast and ovarian cancer." (PMID 35158994, 2022). "In this study, we analysed cancer worry and the course of cancer worry over time among BRCA1/2-PV carriers up to 12 months after surgery to prevent ovarian cancer." (PMID 34997316, 2022). "In ovarian cancer, analysis of samples from the ARIEL2 trial of rucaparib maintenance therapy found RAD51C and RAD51D mutations as well as high-level BRCA1 promoter methylation to be associated with PARPi sensitivity." (PMID 36970052, 2022). "A positive correlation was identified between the expression of NUSAP1 and BRCA1/2 in ovarian cancer." (PMID 35739489, 2022). "Ovarian cancer (OC) patients with BRCA1/2m had a significantly longer OS than those with BRCA1/2 wt across 24 studies reporting BRCA1m and BRCA2m, with an HR of 0.7 (0.6–0.8)." (PMID 35909902, 2022). "Pathogenic variants of BRCA1 and BRCA2 only explain the genetic cause of approximately 10% of hereditary breast and ovarian cancers (transmitted to offspring), underscoring the clinical importance of testing other DNA repair genes." (PMID 35785170, 2022). "In Pakistan, the prevalence and penetrance estimates for BC suggest that dominant BRCA1 and BRCA2 mutations are significant contributors to breast and ovarian cancer in our population." (PMID 36268285, 2022). "Structurally, BARD1 has homologous domains to BRCA1 that aid their heterodimer interaction to inhibit the progression of different cancers such as breast and ovarian cancers following the BRCA1-dependant pathway." (PMID 35650591, 2022). "Previous studies have shown that BRCA1 is an important tumor suppressor gene responsible for DNA damage repair, and play complex roles in the occurrence and progression of ovarian cancer." (PMID 36703740, 2022). "This explains the fact that individuals who have mutations in the BRCA1 and BRCA2 genes have an increased risk of developing different types of cancer, such as breast and ovarian cancers." (PMID 35805026, 2022). "In the course of our study, the ovarian cancer gene panel consisted of the five core genes (BRCA1, BRCA2, BRIP1, RAD51C and RAD51D), and it is likely that the gene panel will be expanded with other cancer genes, such as PALB2, in the near future." (PMID 34617209, 2022). "Collectively, these results suggested that miR-9-5p/BRCA1 axis played a crucial role in the mechanism underlying the synergy between Cur and PTX in ovarian cancer." (PMID 36703740, 2022). "To identify genetic modifiers of BRCA1/2, we carried out a whole-genome sequencing study of 66 ovarian cancer patients that were enriched with BRCA carriers, followed by validation using data from the Pan-Cancer Analysis of Whole Genomes Consortium." (PMID 35625955, 2022). "BRAF V600E and PIK3CA E542K were predominantly associated with thyroid cancer and ovarian cancer, respectively, whereas ERBB2 amplification, BRCA1/2 variant, and KRAS G12C were widely detected across various cancer types." (PMID 36088851, 2022).
ovarian carcinoma (continued). "By reporting on the psychological impact of BRCA1/2 tumour genetic testing for ovarian cancer in Ontario, we hope to inform the successful implementation of tumour genetic testing at other institutions and for additional tumour types." (PMID 35418215, 2022). "Reflecting the growing understanding that HRR-deficiency was the result of more than just BRCA1 or BRCA2 defects, niraparib was FDA approved for HRR-deficient advanced ovarian cancer in 2019." (PMID 36230543, 2022). "Approximately 5–10% of all BCs have family history of breast or ovarian cancer, and women with germline mutations in breast cancer type 1 (BRCA1) and type 2 (BRCA2) are of greater risk of developing breast or ovarian cancer." (PMID 36140723, 2022). "Patients who carried both BRCA1/2 mutations and PPARGC1A mutations were diagnosed with breast or ovarian cancer at a significantly younger age." (PMID 35625955, 2022). "DNA repair defects caused by BRCA1 and BRCA2 missense variants increase the risk of developing breast and ovarian cancers." (PMID 35729312, 2022). "Conversely, a long-term assessment of improved DOR and OS seems more suitable to determine the therapeutic advantage of the drug combination in patients responsive to PARPi, such as in the case of BRCA1/2-mutant or otherwise HR-defective ovarian cancer." (PMID 36428727, 2022). "Compared to ovarian cancer patients with tumors that were BRCA1/2 wt, ovarian cancer patients with tumors harboring BRCA1/2m had a better OS (HR = 0.67 (95% CI = 0.58–0.77))." (PMID 35909902, 2022). "Further, BRCA1 signaling common to both breast and ovarian cancer also has the capability to induce NF-κB activity." (PMID 36531159, 2022). "Women are tested to search for BRCA1 or BRCA2 germline mutations, especially when diagnosed with early-onset breast and/or ovarian cancer." (PMID 35448177, 2022). "Both cases provide further evidence for the gynaecological cancer risk from mosaicism of BRCA1/BRCA2, which has so far only been reported in a single case of BRCA2 mosaicism in a woman with ovarian cancer." (PMID 36068545, 2022). "Standard guidelines identified germline mutations in BRCA1 and BRCA2 genes in 15% of women affected with ovarian cancer, whereas somatic mutations in an additional 7%." (PMID 36010253, 2022). "For BRCA1, family history of ovarian cancer was strongly enriched in female breast, ovarian, and pancreatic cancers." (PMID 35420638, 2022). "After the discovery of the BRCA1 and BRCA2 genes in the 1990s, the first guidelines for the care of high-risk individuals with hereditary breast and ovarian cancer stated that “there was insufficient evidence to recommend for or against prophylactic surgery”." (PMID 35805017, 2022). "During the first three years after epithelial ovarian cancer diagnosis, progression-free survival was better for BRCA1 (HR 0.88, 95% CI 0.74–1.04) and BRCA2 (HR 0.58, 95% CI 0.41–0.81) patients than for sporadic patients." (PMID 36137114, 2022). "PDX models can better represent the personal therapeutic efficacy of PARPis in epithelial ovarian cancer than BRCA1/2mut, HRD+, and platinum sensitivity." (PMID 36230574, 2022). "Therefore, BRCA1-deficient ovarian cancer cells may develop two ways to resist cell death." (PMID 35517499, 2022). "Many studies showed that increasing DNA damage of cancer cell and inhibiting HR repair pathways are the major methods to improve the treatment efficiency of olaparib (Ola) in BRCA1 wild-type ovarian cancer 19-21." (PMID 35280680, 2022).
ovarian carcinoma (continued). "Genotyping of 21 mutations in BRCA1, BRCA2, RAD51C, PALB2, and CHEK2 genes was performed for 102 BOT patients, 167 cases of ovarian cancer G1, and 1743 healthy controls." (PMID 35313928, 2022). "Specifically, BRCA1 accounts for 81% of breast–ovarian cancer families, while BRCA2 only accounts for 14% of these families." (PMID 35740092, 2022). "In our study’s for 56% (10/18) of all patients with BRCA1 origin ovarian cancer the PV was located in the OCCR published in the study of Rebbeck15, whereas for BRCA2 origin ovarian cancer no PV were located in the ovarian cluster region." (PMID 35469032, 2022). "Beyond breast and ovarian cancer, prostate and pancreatic cancer also have targetable homologous recombination deficiency (HRD) beyond the well-known BRCA1 and BRCA2 with relevance that exceeds diagnostic purposes." (PMID 35740616, 2022). "Along with defects in BRCA1 and BRCA2, other genes that function in homologous recombination repair (HRR) are mutated in ovarian cancer, albeit at lower frequencies, including RAD51C, RAD51D, BRIP1, PALB2, and ATM." (PMID 35223797, 2022). "As measured by RAD51 focus formation, restoration of HR is shown to be acquired before restoration of fork protection in a panel of isogenic olaparib-resistant BRCA1 mutant ovarian cancer cells." (PMID 35886427, 2022). "When BRCA1-null ovarian cancer cells were rescued with the wild-type, BRCA1 overexpression successfully blocked NF-κB activation and decreased oxidative stress within the microenvironment." (PMID 36531159, 2022). "Hereditary breast and ovarian cancer (HBOC) syndrome has increased predisposition to breast and/or ovarian cancer, and 24% of families with HBOC were associated with the germline pathogenic variants in BRCA1/2." (PMID 36463302, 2022). "According to the gene map of ovarian cancer patients, approximately 59% of all epithelial ovarian cancers and 50% of all high-grade advanced ovarian carcinomas retain BRCA1/2 expression." (PMID 35280680, 2022). "Recently, BRD4 inhibitor JQ1 and CDK4/6 inhibitor palbociclib have been shown to inhibit HR and sensitize BRCA1/2 wild-type ovarian cancers and other cancers to PARPi." (PMID 36539830, 2022). "Targeted multigene panel testing involves the screening of various established hereditary breast and ovarian cancer genes simultaneously at costs often reported as lower than testing for BRCA1 and BRCA2 alone." (PMID 36568162, 2022). "In conclusion, significant progress has been made in elucidating the role of BRCA1 and BRCA2 and their mutations in the risk and prognosis of epithelial ovarian cancer." (PMID 35147092, 2022). "Loss-of-function variants in the BRCA1 and BRCA2 susceptibility genes predispose carriers to breast and/or ovarian cancer." (PMID 35665744, 2022). "Whereas ovarian cancer cells with BRCA1/2 mutations are sensitive to the PARP inhibitor rucaparib, multiple cell lines with wild-type BRCA1/2 show varying sensitivity to rucaparib." (PMID 35736348, 2022). "The BET bromodomain inhibitor JQ1 synergized with the PARP inhibitor olaparib in BRCA1/2 wild-type ovarian cancer both in vitro and in vivo and was correlated with the suppression of both TOPBP1 and WEE1." (PMID 36139634, 2022). "Taken together, all these data demonstrated that miR-9-5p functions through regulating BRCA1 in ovarian cancer cells." (PMID 36703740, 2022). "Whereas both BRCA2 and BRCA1 are commonly altered in breast and ovarian cancer, BRCA1 alterations are less common than BRCA2 alterations in prostate cancer." (PMID 35768576, 2022). "In another cohort of this study enrolling patients with germline BRCA1/2m platinum-sensitive relapsed ovarian cancer, showed ORR of 63% and a 12-week DCR of 81%." (PMID 36533080, 2022). "One of the predisposing factors for epithelial ovarian cancer (EOC) is germline mutation in tumor suppressor genes, such as BRCA1 and BRCA2 (BRCA1/2)." (PMID 36143252, 2022).
ovarian carcinoma (continued). "Many studies demonstrated that germline and somatic BRCA1 and/or BRCA2 mutations are related to a better prognosis in ovarian cancer patients." (PMID 35267543, 2022). "Olaparib was the first PARP inhibitor approved for patients with BRCA1/2 mutant, advanced-stage ovarian cancers in 2014." (PMID 36284291, 2022). "Mutations in BRCA1 and PALB2 genes were significantly associated with the high risk of ovarian cancer G1, while CHEK2 missense mutation (c.470T>C) was associated with 2-times elevated risk of BOT." (PMID 35313928, 2022). "An additional explanation for BRCA1’s downregulation-mediated enhancement of cisplatin sensitivity comes from its recently discovered role in the regulation of ovarian cancer cells’ metabolism." (PMID 36230683, 2022). "Germline mutations in HRR genes BRCA1/2 and PALB2 are known to associate with hereditary breast cancer and ovarian cancer, which have also been described in pancreatic cancer and prostate cancer." (PMID 35281878, 2022). "The results showed that similar to BRCA1/2 in breast and ovarian cancer, BRCAness genes were the prognostic markers for multiple cancer types." (PMID 36497135, 2022). "As expected, PVs in BRCA1/2 were more frequent in subjects with a personal and/or family history for breast/ovarian cancer (12/76, 15.8%)." (PMID 36139606, 2022). "Most of the information on BRCA1 and BRCA2 pathogenic mutations are tailored to women due to the availability of effective surgical risk reduction procedures for breast and ovarian cancer among women." (PMID 35303741, 2022). "In this retrospective multicenter study, we investigated the prevalence of PVs in BRCA1/2 and 23 non-BRCA1/2 genes using a sample of 614 patients with mBC, recruited through the centers of the German Consortium for Hereditary Breast and Ovarian Cancer." (PMID 35805063, 2022). "The majority of PVs conferring ovarian cancer risk occur in the BRCA1 or BRCA2 genes (herein: BRCA1/2); however, additional ovarian cancer risk genes have also been identified." (PMID 35418215, 2022). "Women with inherited pathogenic variants in the BRCA1 and BRCA2 genes have a high risk of developing both breast and ovarian cancer." (PMID 35123550, 2022). "In HRR pathway, germline or somatic BRCA1 and BRCA2 mutations are associated with increased risks of solid tumors, especially breast and ovary cancers." (PMID 35328658, 2022). "Recently, it was reported in a small study that patients with ovarian cancer harboring the Mexican BRCA1 founder CNVs had a better RFS than those with other types of BRCA1 PVs." (PMID 35875314, 2021). "This study investigated the functional impact of platelet-activating factor acetylhydrolase on BRCA1 mutant ovarian cancer biology and its crosstalk with the Wnt signaling pathway." (PMID 34206491, 2021). "As one of the nine significantly mutated genes in ovarian cancer, CDK12 involves the transcription of BRCA1 and other DNA repair genes." (PMID 34680987, 2021). "Several founder mutations in the BRCA1, BRCA2, PALB2, RAD51C, and CHEK2 genes are associated with breast and ovarian cancer." (PMID 33670479, 2021). "For example, hypermethylation of the BRCA1 gene CpG island mainly occurs in breast and ovarian cancer, while hypermethylation of the hMLH1 gene is commonly found in colon, stomach and endometrial cancers." (PMID 33509178, 2021). "The mechanisms driving the differential association between BRCA1 and BRCA2 mutations with progression and survival in breast and ovarian cancers are not completely understood." (PMID 33525353, 2021).
ovarian carcinoma (continued). "Comparatively, the BRCA1 mutated UWB1.289 cancer cells demonstrated a much lower PARP1 and a reduced PARP2 mRNA transcription than the other ovarian cancer cell lines tested (t-test, p < 0.001)." (PMID 34440232, 2021). "Our data revealed that the active lactam steroid alkylator ASA-B exhibited a significantly higher anticancer activity in the BRCA1-null ovarian cancer cell line UWB1.289 than in the respective BRCA1 wild-type UWB1.289 + BRCA1 ovarian cancer cell line." (PMID 34440232, 2021). "Recent studies have demonstrated high sensitivity and specificity of detecting germline variants in BRCA1/2 using formalin-fixed paraffin-embedded (FFPE) specimens from breast and ovarian cancer cases." (PMID 34834546, 2021). "In ovarian cancer, MMR deficiency is the most common cause of hereditary ovarian cancer after BRCA1 and BRCA2 mutations." (PMID 34207450, 2021). "In cancer treatment, precision medicine refers to targeted therapy based on biomarkers, including proteins and genes: for example, EGFR in lung cancer and BRCA1/2 in ovarian cancer." (PMID 34209310, 2021). "In women with a hereditary ovarian cancer syndrome the cumulative chance of developing ovarian cancer to the age of 80 years is 44% for BRCA1 and 17% for BRCA2 carriers." (PMID 34565426, 2021). "The present limitations in the pathogenicity prediction of BRCA1 and BRCA2 (BRCA1/2) missense variants constitute an important problem with negative consequences for the diagnosis of hereditary breast and ovarian cancer." (PMID 34207612, 2021). "The relationship between BRCA1 methylation and drug resistance in ovarian cancer still needs further verification." (PMID 34289901, 2021). "Herein, for the first time, among Belarussian ovarian cancer patients, we detected BRCA1 c.3756_3759delGTCT, c.68_69delAG, c.1687C > T, and BRCA2 c.658_659delGT mutations." (PMID 33478551, 2021). "BRCA1 and BRCA2 mutations were the most prevalent with the positive rate of 1.3% in the general cohort and 5.1% in breast or ovarian cancer patients." (PMID 35070997, 2021). "Pathogenic variants in the BRCA1 and BRCA2 genes are associated with about 20% of familial breast and ovarian cancers." (PMID 33319336, 2021). "In Poland, founder mutations in BRCA1, BRCA2, PALB2, CHEK2, and RAD51C have been associated with familial breast and ovarian cancer." (PMID 33670479, 2021). "Individuals with hereditary mutations in BRCA1 and BRCA2 are predisposed to a higher risk of breast or ovarian cancer." (PMID 33674888, 2021). "Similar to BRCA1, germline mutations in BRCA2 predispose patients to breast and ovarian cancer and genome instability." (PMID 33996823, 2021). "Many existing software packages are limited to estimating risks based on mutations in well-known cancer-related genes, such as BRCA1 and BRCA2 in breast and ovarian cancer." (PMID 34406119, 2021). "•Patients with germ-line mutation in BRCA1 or BRCA2 have a significant increased risk of breast and ovarian cancer." (PMID 33996049, 2021). "PVs in BRCA1 or BRCA2 were identified in 2.4% of all tested women but in 6.1% of women with a history of ovarian cancer (~ 2.5-fold increase)." (PMID 33926482, 2021). "Improved mechanistic understanding and higher resolution laboratory identification of BRCA1/2 genetic variation subtypes and non-BRCA1/2 genetic aberrations contribute to the clinical care that breast and ovarian cancer patients receive." (PMID 34711195, 2021). "According to the literature, variable levels of BRCA1 promoter methylation in ovarian cancer have been previously reported, ranging from 5–90%." (PMID 35008168, 2021).